HIF1A (hypoxia inducible factor 1 subunit alpha)
Diseases named in the same sentence as HIF1A in open-access papers (continued):
Sharing a sentence is not in itself a finding about the gene and the disease.
tumor (continued). "TME parameters such as hypoxia and redox status, reflected by HIF-1α protein expression and glutathione (GSH) content in tumor tissue, can inform clinical decisions regarding VC monotherapy versus combination strategies." (PMID 40950984, 2025). "Vitamin C can reduce HIF-1α activity, therefore reducing the expression of pro-angiogenic factors such as VEGF, restricting tumor growth." (PMID 39857427, 2025). "A preclinical study discovered that, when BAP1 is mutated, the levels of HIF-1α are significantly reduced and suggested that the improved prognosis observed in PM with BAP1 mutations may be linked to the reduced HIF-1α levels in the tumor cell and in the microenvironment." (PMID 40361508, 2025). "Hypoxia can stimulate the up-regulation of HIF1A, ADAM10, and sMICA, resulting in the reduction of NKG2D in NK cells and tumor cells and evade immune surveillance and NK cell-mediated lysis." (PMID 40296917, 2025). "The role of CCT complex in this context, particularly in relation to the impaired function of PHD3, VHL and HIF-1α, warrants further investigation to elucidate its potential impact on HIF-dependent signaling and tumor biology." (PMID 41516249, 2025). "The current work found that the downstream targets of HIF-1α activity, metabolic markers Ang2, GLUT1, LDHA, and PDK1, which equip the tumor for survival and growth under hypoxic conditions, were also downregulated by anlotinib plus bevacizumab." (PMID 41041327, 2025). "HIF-1α inhibits E-cadherin transcription by up-regulating its repressors, including ZEB1, ZEB2, transcription factor 3, TWIST, and SNAIL, thereby promoting tumor cell metastasis." (PMID 41585262, 2025). "ELISA, western blot, and xenograft tumor experiments were implemented to confirm the impact of LARS and the LRPPRC/HIF-1α axis on malignant progression and glycolysis." (PMID 40775462, 2025). "Paradoxically, in the TME, tumor-derived succinate becomes protumorigenic, CRC-secreted succinate recruits macrophages via SUCNR1 and drives TAM polarization through PI3K/AKT and HIF-1α activation." (PMID 41488637, 2025). "For instance, APE1-mediated reduction of HIF-1α enhances hypoxia-responsive transcription (e.g. VEGF expression), promoting tumor angiogenesis." (PMID 41446759, 2025). "(K) Western blotting of macrophage pro-tumor indicators (VEGF, MMP9, TGF-β, and HIF-1α) in S100a4-OE MH-S." (PMID 40658605, 2025). "Hydroxylation, catalyzed by enzymes such as prolyl hydroxylases, plays a role in stabilizing hypoxia-inducible factor-1 alpha (HIF-1α), which promotes tumor adaptation to hypoxic conditions." (PMID 40427595, 2025). "In tumors expressing HIF1A, elevated EPO expression contributes to tumor progression by stimulating EPOR and activating downstream signaling pathways, such as JAK2-STAT5." (PMID 40332447, 2025). "First, CAFs directly promote tumour proliferation and metastasis by secreting growth factors (e.g., CXCL11, CCL5): CAF-derived CCL5 enhances HCC metastasis by triggering the HIF1α/ZEB1 axis, while CXCL11 directly promotes HCC cell proliferation." (PMID 40495147, 2025). "Future studies using 3D organoid or in vivo xenograft models of EAC will be essential to determine the physiological relevance of dual (HIF1α and NT5E) inhibition on tumor growth, angiogenesis, immune modulation and metastasis." (PMID 41463265, 2025). "RCC is characterized by high HIF activity, particularly involving HIF-1α and HIF-2α, which orchestrate distinct but complementary roles in tumor progression." (PMID 41281744, 2025). "It was found that HIF1α, STAT3, and MYC were highly expressed in tumor tissues and were positively correlated with Linc01559 expression (Figure A2a)." (PMID 40722682, 2025). "They observed that the transcriptional selectivity favoring HIF-2α over HIF-1α correlated with their respective impacts on tumor growth, with HIF-2α promoting tumor proliferation and HIF-1α exerting an inhibitory effect." (PMID 39470609, 2025).
tumor (continued). "HMGB1 promotes the activation of the PI3K/AKT signaling pathway, leading to the upregulation of HIF-1α, which in turn enhances VEGF expression, inducing tumor angiogenesis and cell migration." (PMID 40396172, 2025). "Through pathways like HIF-1α, YAP1, and NF-κB, ROS in the tumor microenvironment can control PD-L1 expression on cancer cells, frequently encouraging its upregulation." (PMID 41439968, 2025). "Studies have shown that hypoxia‐induced HIF‐1α upregulates FAO‐related genes in gastric cancer, providing metabolic flexibility for tumor cells under adverse conditions." (PMID 40391753, 2025). "Giant tumors not only indicate higher tumor load, but also are accompanied by strong angiogenesis and hypoxia environment, which activates HIF-1α, VEGF and other pathways to promote tumor cell invasion, metastasis and immunosuppression." (PMID 41200181, 2025). "Beyond its pro-apoptotic effects, nelfinavir also modulates the TME by downregulating hypoxia-inducible factor 1 alpha (HIF-1α) and VEGF, thereby improving tumor oxygenation and suppressing angiogenesis." (PMID 41211420, 2025). "HIF-1α can promote the IL-2 and IL-12 cytokine-stimulated OXPHOS response, and promote the killing effect of NK cells on the tumor tissues." (PMID 40696413, 2025). "Building upon our prior discovery of the NAT10/SEPT9/HIF-1α positive feedback loop driving glycolytic addiction in GC11, this work unveils a novel NAT10/XIST/YAP1/VEGFA axis governing tumor vascular ecology." (PMID 40860183, 2025). "UMAP distribution showed that AKT1 and ESR1 were primarily expressed in tumor cells, SRC and IL6 were concentrated in the Myeloid subpopulation, while MTOR and HIF1A exhibited a broader distribution across multiple cell types." (PMID 40746726, 2025). "Grinding tumor tissues and conducting Western blot experiments demonstrated that CuB effectively reduced the protein expression levels of ZFP91, HIF-1α, c-Myc, Cyclin D1, VEGF, and MMP-9 in tumor tissues." (PMID 40860815, 2025). "This event upregulates hypoxia-inducible factor-1α (HIF-1α) and pyruvate kinase M2 (PKM2), thereby enhancing glycolysis and glucose uptake to support rapid tumor proliferation." (PMID 40666095, 2025). "Fluorescent staining of tumour sections for hypoxia and validated markers in the H22 tumour-carrying mouse model showed that PFH@LSLP enhances anti-tumour effects by reducing hypoxic zones and increasing HIF-1α and CXCR4 expression in PDX HCC tumours." (PMID 40092984, 2025). "The rapid proliferation of tumor cells triggers an overexpression of pro-angiogenic factors, including VEGF, largely regulated by HIF-1α." (PMID 39981236, 2025). "By measuring lactate and ATP production, we found that glycolysis was inhibited in hypoxic tumor cells treated by L-OHP after siALDOC knockdown, demonstrating HIF-1α exerted a regulatory effect on glycolysis via ALDOC." (PMID 40535800, 2025). "Elevated levels of HIF-1α activate glycolysis-related genes such as HK2 and LDHA, supplying energy and metabolic intermediates essential for tumor growth." (PMID 40255400, 2025). "Hypoxia, along with the overexpression of hypoxia-inducible factors 1 and 2 alpha (HIF-1α and HIF-2α), which are key mediators of the tumor response within the TME." (PMID 40248695, 2025). "The temporal “HIF switch” from HIF-1α in acute hypoxia to HIF-2α in chronic states enables sustained vascular maturation and energy balance, reinforcing tumor progression." (PMID 40869364, 2025). "This HIF-1α/IL-6/FPN pathway reshapes the iron distribution within the TME, favoring tumor cell proliferation and impairing anti-tumor immune responses." (PMID 40861444, 2025). "ALDH1 generates retinoic acid, which activates the AKT and HIF-1α/vascular endothelial growth factor (VEGF) pathways, enhancing stemness and subsequently promoting aggressive tumor proliferation." (PMID 39888413, 2025).
tumor (continued). "Under hypoxic conditions, HIF1A is not only a binding partner of CARM1 but also plays a key role in its regulatory action, forming a positive feedback loop to enhance tumor cell adaptation to the hypoxic environment." (PMID 39995416, 2025). "Together, these results suggest that Myr-NE treatment results in efficient inhibition of PAM proteins and VEGFR2 accompanied by significant downregulation of HIF-1α, Ki67, and MMP9 proteins, effectively reducing the tumor proliferation in TNBC xenografts." (PMID 40552278, 2025). "Meanwhile, LARS promoted tumor growth and raised the expression of LA (the product of glycolysis) and that of HK2, GLUT1, and HIF-1α, the key enzymes in glycolysis, which were reversed upon 2-DG treatment." (PMID 40775462, 2025). "Anti-tumor responses are also negatively influenced by the enhancement of M2 polarization by inducing arginase-1 (ARG-1), transcriptional repressors, HIF-1α and IL-6 via the upregulation of MCT-4 expression and glycolytic rate promoted by lactate." (PMID 40092297, 2025). "While CD73 inhibition alone modestly reduced EAC cell viability, combined inhibition of HIF-1α and CD73 synergistically decreased tumor cell survival, particularly under hypoxic conditions, and significantly altered extracellular adenosine metabolism." (PMID 41463265, 2025). "GPD1L downregulation represents a hallmark of CRC progression, with affecting the expression of HIF-1α and MMP9 significantly impeding malignant behaviors, nominating it as a candidate tumor suppressor in colorectal neoplasia." (PMID 40538846, 2025). "Impaired HIF-1α stabilization leads to a reduction in VEGF expression, thereby limiting neovascularization and restricting the tumor’s ability to acquire nutrients and oxygen for sustained growth." (PMID 40076537, 2025). "Abnormal expression of metalloproteinases is regulated by HIF-1α, which induces the expression of MMP2, MMP9, ADAM10, etc., in tumor cells, hydrolyzing MICA and MICB on the surface of tumor cells and mediating immune escape." (PMID 40563539, 2025). "The reduction in hypoxia, as evidenced by the decreased expression of HIF-1α in the CHL-GCS-IO NPs group, directly correlated with improved tumor oxygenation and increased therapeutic efficacy." (PMID 40514659, 2025). "Hypoxic tumor cells secrete chemokines (e.g., CCL2), hypoxia-inducible factors (HIF-1α, HIF-2α), and endothelin-2, which direct macrophage chemotaxis into the tumor core." (PMID 40422235, 2025). "The TNBCvax group (a combination of all three antigens) and the individual IGF-1R, HIF-1α, and TOP2A vaccination groups showed significantly reduced tumor growth rates compared to the CpG control group." (PMID 40969744, 2025). "Given the significant roles of hypoxia-inducible factor 1 alpha (HIF-1α) and TGF-β under the hypoxic conditions of the tumor microenvironment, we induced hypoxia in tumor cells using cobalt chloride (CoCl2) with and without inhibition of miRNAs." (PMID 40943648, 2025). "In conclusion, our study elucidates a novel PRCC‐TFE3/HIF1α/SREBP1 axis that drives metabolic reprogramming and tumor growth in TFE3‐RCC." (PMID 39807625, 2025). "All these processes are considered to impact tumor growth and progression, and PI3K/AKT signaling represents an upstream regulator of HIF-1α, promoting its stability and activation under hypoxia." (PMID 41041327, 2025). "Hypoxia and HIF-1α impair the function of CD8+ T cells, the primary effectors of anti-tumor immunity." (PMID 39981236, 2025). "In early tumorigenesis, PKM2 is already overexpressed and cooperates with HIF-1α and GLUT1 to activate the glycolytic program, establishing an early Warburg effect axis that provides metabolic advantages to emerging tumor cells." (PMID 40842995, 2025). "Under hypoxic conditions, HIF-1α can stimulate the expression of SOX2 and OCT4, thereby facilitating tumor cell self-renewal and differentiation processes." (PMID 39781344, 2025).
tumor (continued). "Among different hypoxic conditions, cyclic hypoxia is particularly potent as it increases hypoxia-inducible factor-1 alpha (HIF-1α) and tumor aggressiveness, fostering a partial EMT phenotype that enables collective cell migration as clustered CTCs or emboli." (PMID 41381723, 2025). "In contrast, tumor-derived NOX4-produced hydrogen peroxide induces M2 polarization through HIF-1α stabilization, creating chemokine gradients (CCL7/IL-8) that recruit CCR1+ immunosuppressive macrophages to support tumor progression." (PMID 40733095, 2025). "Among these derivatives, N-butyryl-5-methoxytryptamine (NB-5-MT) exhibited the highest anti-tumor potency, resulting in reduced expression of HIF-1α, decreased transcription of HIF-1α gene targets, and inhibition of angiogenesis both in vitro and in vivo." (PMID 39470609, 2025). "HBOT reduces HIF-1α stability, leading to a 52% decrease in miR-145 expression, thereby restoring the anti-angiogenic function of TSP1 and inhibiting abnormal tumor angiogenesis." (PMID 40552269, 2025). "Interestingly, in vivo experiments revealed significantly smaller tumor volumes and longer survival times after the individual knockout of either HIF1α or HIF2α compared to those in the control group, which may be due to microenvironmental differences between in vivo and in vitro studies." (PMID 40370575, 2025). "For instance, knockdown of HIF-1α significantly reverses hypoxia-induced migration and downregulates the expression level of VEGFs in GBC, while the overexpression of HIF-1α is associated with LNM, suggesting HIF-1α may contribute to tumor migration via the HIF-1α/VEGF signaling pathway in GBC." (PMID 40564091, 2025). "TAMs support tumor progression by secreting pro-migratory cytokines like IL-6 and induce tumor metastasis through PI3K/AKT and HIF-1a signalling." (PMID 40931345, 2025). "HIF-1α-dependent activation of S100A6 involves TET2 enrichment and reduced DNMT3a binding, linking epigenetic remodeling to tumor progression." (PMID 41303477, 2025). "In the hypoxic TME, stabilization of HIF-1α not only enhances glycolytic flux through the upregulation of HK2 and PDPK1, but also supports tumor cell motility and invasiveness." (PMID 41450919, 2025). "Previous studies have reported upregulation of ANXA2 and HIF1A in MM, whereas MAST4 exhibits tumor-suppressive downregulation." (PMID 41403951, 2025). "In the subgroup of patient tumour samples with an elevated accumulation of IL‐11, EMT genes (SNAI1, AXL and TWIST1) and hypoxia factor 1 (HIF1A) were over‐expressed compared with the subtype with a lower accumulation of IL‐11." (PMID 40673604, 2025). "Over-expressed HIF-1α then enters the nucleus, where HIF-1α methylates the HRE of the PTGIS gene, thereby preventing PTGIS transcription and tumor proliferation." (PMID 37475553, 2024). "In this regard, PX-478, an inhibitor of HIF-1α, was used to confirm the effect of HIF-1α blockage on U87 cell lines and its contribution in tumour progression." (PMID 38698968, 2024). "Promoted tumor cell invasion, EMT, EC migration, angiogenesis and sprouting (ex vivo, in vitro) through HIF-1α." (PMID 38745756, 2024). "Their findings underscore the potential of targeting HIF1α pathways, including through SMURF2 modulation, to impede tumor progression." (PMID 39697237, 2024). "Treatment of tumor cells with ET1 and ET3 resulted in increased HIF-1α levels, increased aggressiveness and neovascularization." (PMID 38785410, 2024). "This function shifts under hypoxic tumor conditions, where SMURF2 is crucial for the polyubiquitination and proteasomal degradation of HIF1α." (PMID 39697237, 2024). "CARM1 cooperates with HIF1A to occupy the promoters of CDK4, Cyclin D1, β-Catenin, HIF1A, MALAT1, and SIX1 and promote tumor progression in TNBC." (PMID 38476024, 2024).
tumor (continued). "Beyond its role in HIF1α regulation, SMURF2 exerts extensive control over cellular processes central to tumor progression, including chromatin remodeling, DNA damage repair, ferroptosis, and cellular stress responses." (PMID 39697237, 2024). "The synergistic effects of HIF-1α on VEGF, as evidenced by string analysis data, underscore its crucial role in increasing mRNA levels and expression in tumor cells." (PMID 38542288, 2024). "We assessed the hypoxia-related gene expression (HIF1A, EGLN1-3, CA9, GLUT1, VEGF) by qPCR in our study group of 96 tumor tissues and 96 adjacent normal tissues of HNSCC patients." (PMID 38928200, 2024). "On the contrary, a statistically significantly higher number of cells producing ASPH (p < 0.0001), HIF1A (p < 0.0001), GLUT1 (p < 0.0001), and MMP13 (p < 0.05) proteins were detected in the HPV-positive tumor group than in the HPV-negative sample group." (PMID 38858774, 2024). "The most prominently studied subunits are the oxygen-dependent alpha subunits HIF-1α and HIF-2α, which are both necessary for cancer cell viability in the hypoxic tumor microenvironment." (PMID 38727267, 2024). "A hypoxic environment leads to hypoxia-induced factors (HIF) such as HIF-1α and HIF-1β, which induce the production of VEGF and thus tumour progression and angiogenesis." (PMID 38399237, 2024). "We demonstrated that USP11 overexpression promotes HIF‐1α stabilization and enhances glycolysis through PDK1 and LDHA‐related pathways, eventually leading to tumour cell proliferation and metastasis." (PMID 38229475, 2024). "The clinical correlation between elevated expression levels of HIF-1α and HIF-2α and heightened rates of distant metastasis, as well as poorer overall survival outcomes, has been observed across various tumor types." (PMID 39557851, 2024). "Western blot analysis suggested that the HIF‐1α and VEGF‐A levels were higher in AGS‐DDR1 tumor xenografts, consistent with the in vitro findings." (PMID 39024501, 2024). "For example, targeting HIF1A along with EGFR or VEGF inhibitors can disrupt both hypoxia adaptation and angiogenesis, which is crucial for tumor growth and metastasis." (PMID 39458948, 2024). "HIF-1α and HIF-2α share structural similarities, yet their roles differ across tumor and cell types." (PMID 38799423, 2024). "HIF‐1α upregulates vascular endothelial growth factor (VEGF), a crucial mediator of angiogenesis, thereby facilitating tumor expansion." (PMID 39415849, 2024). "In pancreatic stellate cell (PSC), HIF-1α can induce the expression of HDGF and the increased level of HDGF shows anti-apoptotic and pro-fibrotic effects, which can maintain tumor lesions." (PMID 38725864, 2024). "Curcumol reduces the protein levels of HIF-1α and VEGF in the tumor tissues and inhibits crosstalk between STAT3 and HIF-1α pathways, thereby restricting tumor growth and progression." (PMID 39690423, 2024). "The overexpression of HIF-1α and HIF-2α in LUAD suggests the activation of hypoxia-responsive signaling pathways, potentially contributing to tumor aggressiveness and adversely affecting patient prognosis." (PMID 38356715, 2024). "Copper mediates the binding of HIF-1α to target gene promoters, even under normoxic conditions, stabilizing HIF-1α and promoting expression of genes like VEGF, which drives tumor angiogenesis." (PMID 38693584, 2024). "We analyzed HIF-1α, the protein of the hypoxia pathway and one of the EMT signaling pathway components, to examine tumor cells' resistance against the treatments used." (PMID 38213726, 2024). "Tumor cell Exos with specific cytokines TGF-β, HIF-1α, β-Catenin, and Caveolin-1 can increase the motility of neighboring cells within the TME." (PMID 38360641, 2024). "In vitro data using human cell lines derived from metastatic PCa and BCa tumours (DU145 and MDA-MB-231) demonstrates that hypoxia (0.5% O2) increases tumour cell expression of PD-L1 in a HIF-1α dependent manner leading to increased T cell apoptosis." (PMID 38352889, 2024).